WNT1 (Wnt family member 1)
Diseases named in the same sentence as WNT1 in open-access papers (continued):
Sharing a sentence is not in itself a finding about the gene and the disease.
breast cancer (continued). "Enrichment analysis performed for genes associated with breast cancer stem-like cells revealed that residual tumor cells in both the HER2/neu and Wnt1 models upregulated genes associated with human breast cancer TICs (p value HER2/neu = 0.001; p value Wnt1 = 2.23E−12)." (PMID 34088357, 2021). "In addition, Becn1+/+ mice displayed decreased tumorigenesis compared with Becn1+/− mice in a Proto-Oncogene WNT1 (WNT1)-driven breast cancer model as well as in spontaneous breast cancer formation following parity." (PMID 34207792, 2021). "Likewise, the ablation of FAK expression or the disruption of its kinase activity in a mouse model of a mouse mammary virus tumor (MMTV)-Wnt1-driven breast cancer, enhanced tumor cell apoptosis with an increase of cleaved caspase 3-positive cells." (PMID 33562737, 2021). "In mouse mammary tumors consisting of a Wnt1-producing, Hras wild-type luminal subclone and an Hras-mutant basal subclone, it was found that both subclones were necessary for tumor propagation, with a critical dependence on luminally produced Wnt1." (PMID 34771685, 2021). "Wnt1 and Fgf3 expression is upregulated in cases of breast cancer." (PMID 34552611, 2021). "A monoclonal anti-Wnt-1 antibody or Wnt-1 siRNA inhibit could induce apoptosis in a variety of human cancer cell lines including breast cancer." (PMID 33585487, 2021). "The development of estrogen-initiated cells into malignant tumors does not require the involvement of the estrogen receptor (ER), although the ER certainly plays a role in the promotion of cancer cells; the development of mammary tumors in 100% of female ERKO/Wnt-1 mice demonstrated this." (PMID 34361004, 2021). "Besides cell survival, we also examined the effect of FAK deletion on a number of other cellular activities in Wnt1-driven mammary tumor cells." (PMID 32493400, 2020). "In the case of mixed Mychigh/Myclow mammary tumors, such aggressive supercompetition would, of course, be expected to expeditiously eradicate the Wnt1-producing Myclow cells that are the principal source of Wnt1 survival signals keeping the Mychigh cells alive." (PMID 31611367, 2019). "In addition, miR-148a is detected to be downregulated in human breast cancer tissues, and its overexpression can inhibit the migration and invasion of breast cancer cells by targeting WNT-1, while inhibition of miR-148a-3p had the opposite effect." (PMID 30390708, 2018). "Together, these data suggest that Wnt-1 could be a useful biomarker and therapeutic target in breast cancer." (PMID 30558303, 2018). "Hyperactivation of the Wnt pathway is common in breast carcinomas where it is often activated in the absence of downstream mutations, and Wnt1 overexpression in mammary epithelium is sufficient to form basal-like tumors in mice with low metastatic potential." (PMID 30458886, 2018). "In addition, PTEN deletion and PI3K activation were shown to cooperate with Wnt1 to induce mammary tumors." (PMID 28296140, 2017). "A recent study demonstrated that NanogP8 expression alone in the mammary tissue is incapable of inducing mammary tumors but could enhance mammary tumorigenesis and accelerate metastasis of Wnt-1 transgenic mice." (PMID 28881767, 2017). "In addition, overexpression of Wnt1 and Rspo2 in mammary epithelial cells, individually or together, leads to mammary tumor formation and cells exhibit a strong EMT phenotype and are highly metastatic to lung and spleen." (PMID 27420097, 2016). "Wnt1 abrogated HNK-mediated inhibition of invasion of breast cancer cells." (PMID 26036628, 2015). "Our previous studies have shown that Wnt1 regulates MTA1-β-catenin axis in breast cancer cells." (PMID 26036628, 2015). "Wnt1 treatment alone increased invasion of breast cancer cells." (PMID 26036628, 2015). "Wnt1 expression is upregulated in various cancers including breast cancer." (PMID 26036628, 2015).
breast cancer (continued). "Therefore, to further confirm the connection between Wnt/β-catenin signaling and breast cancer metastasis in vitro, we assessed the effects of Wnt1 knockdown on metastasis using in vivo metastatic models of 4T1 cells." (PMID 26202299, 2015). "To examine whether the blockade of Wnt/β-catenin signaling suppresses tumor sphere formation in breast cancer, we generated stable Wnt1 knockdown 4T1 cells." (PMID 26202299, 2015). "Therefore, to further confirm the connection between Wnt/β-catenin signaling and breast cancer metastasis observed in vitro, we assessed the effects of Wnt1 knockdown on metastasis using in vivo metastatic models of 4T1 cells." (PMID 26202299, 2015). "However, the latency period (12–20 months) was very long compared, for example, to Wnt-1 transgenic mice, which develop mammary tumors with a median latency of 6 months." (PMID 24805056, 2014). "This is important because all three PEA3 family proteins are expressed in MMTV/Wnt1 mammary tumors." (PMID 20107508, 2010). "In breast cancers, upregulation of Wnt-1 induces EGFR and Erk 1/2 MAPK activation." (PMID 20828404, 2010). "Further studies showed that in breast cancers, Wnt1 transactivates EGFR, implying that constitutive Wnt signaling might impact not only the canonical pathway but also EGFR activity by augmenting ligand availability." (PMID 20828404, 2010). "Here, we utilized the MMTV/Wnt1 mouse strain to further interrogate the role of PEA3 transcription factors in mammary tumorigenesis based on our previous observation that Pea3 is highly expressed in MMTV/Wnt1 mammary tumors." (PMID 20107508, 2010). "Previous studies have shown an increased abundance of cyclin D1 in Wnt1 mammary tumors." (PMID 20565980, 2010). "Mammary tumors induced by mouse mammary tumor virus (MMTV) infection have revealed oncogenes involved in murine mammary tumorigenesis, and Wnt-1 was the first proto-oncogene discovered as a gene frequently activated in mammary tumors arising in mice infected with MMTV." (PMID 19267898, 2009). "Conversely, blockade of Wnt-1 signaling using Wnt-1 antibodies have been reported to induce apoptosis in a variety of human cancer cell lines, including non small cell lung cancer, breast cancer, colorectal cancer mesothelioma, and sarcoma." (PMID 19778454, 2009). "Wnt-1 was first identified as a protooncogene activated by viral insertion in mouse mammary tumors." (PMID 18570671, 2008). "Although Wnt-1 itself has not been implicated in human breast neoplasms, other Wnt family members are overexpressed in human breast cancer and there is growing evidence that Wnt pathway contributes to maintenance of cancer stem cells." (PMID 18570671, 2008). "For example, estrogen receptor positivity in mammary tumors of wnt – 1 transgenic mice is influenced by collaborating oncogenic mutations rather than wnt-1 per se." (PMID 17880731, 2007). "It will be important to see whether results from the T47D breast cancer model are clinically relevant in primary breast tumors, many of which overexpress Wnt1." (PMID 17897439, 2007). "Furthermore, Wnt1 rescues estrogen receptor-positive (ER+) breast cancer cells from the anti-proliferative effects of 4-hydroxytamoxifen (4-HT) and this activity can be blocked by an EGFR tyrosine kinase inhibitor." (PMID 17897439, 2007).
breast cancer (continued). "Furthermore, an Src kinase inhibitor abolished the effects of Wnt1 on ERK1/2 activation in human breast cancer cell lines and Src kinase activation was increased in SkBr3/Wnt1 cells." (PMID 17897439, 2007). "Therefore, Wnt1 differential gene expression pattern may be used as a prognostic biomarker to predict overall survival of the gastric and breast cancer patients." (PMID 36056132, 2022). "Besides, researchers found that expression of Six3 is negatively correlated with breast cancer malignancy and further studies on the mechanism revealed that Six3 recruits LSD1/NuRD(MTA3) complex to Wnt1 promoters, thus resulting in a reduction of Wnt1 expression levels in breast cancer." (PMID 34545072, 2021). "Indeed, we found that mTOR inhibitor PP242 targeting both mTORC1 and mTORC2 could induce apoptosis in Wnt1-driven mammary tumor cells, supporting a role for mTOR to at least partially mediate FAK regulation of tumor growth and metastasis." (PMID 32493400, 2020). "Moreover, Wnt1 knockdown induced the cytoplasmic accumulation of β-catenin in breast cancer cells." (PMID 26202299, 2015). "Therefore, we asked whether Sca-1 regulates cell migration using a mammary tumor cell line (Wnt1-YL), derived from primary MMTV-Wnt1 tumors." (PMID 22140470, 2011). "Additionally the effects of other mammary tumor promoting oncogenes such as Wnt1 and ras may alter the effects of SRC1 deletion." (PMID 21080969, 2010). "Therefore, the Wnt1/ILK-mediated upregulation of nuclear β-catenin shown both in vitro and in vivo could potentially be responsible for the observed upregulation of FOXA1 expression in the Wnt1/ILK mammary tumors." (PMID 20565980, 2010). "Thus, Wnt signaling may partially override the effects of Rapamycin and prevent cell cycle arrest and apoptosis as shown here for Wnt-1 mammary tumor cells." (PMID 18570671, 2008). "However, EMT does not occur in mammary tumors of mice transgenic for Tgfa, Neu, Notch4, and Wnt1, which indicates that the morphologic features associated with cancer progression are determined by the initiating oncogenic events." (PMID 15535849, 2004). "Leptin activates Wnt1 signaling by upregulating MTA1 expression, which induces EMT in breast cancer cells." (PMID 40565190, 2025). "Bioinformatic analysis using cBioPortal v6.0.0, revealed a positive correlation between USP30-AS1 expression and several Wnt signaling components, including TCF7, WNT1, WNT10, and MMP7, in clinical breast cancer." (PMID 41614739, 2025). "Breast cancer treatment involves targeting key genes involved in cell proliferation, differentiation, and apoptosis, such as PIK3CA, CCND1, HER2, STAT3, WNT1, and KRAS." (PMID 40284420, 2025). "In MDA-MB-231 breast cancer cells, oncogenes such as PIK3CA, CCND1, HER2, and WNT1 were significantly downregulated, particularly in the FEO-CSNP treatment group, indicating the suppression of proliferative and metastatic signaling pathways." (PMID 40284420, 2025). "The WNT ligands WNT1 and WNT3 are involved in the activation of WNT/β-catenin/TCF signaling to promote mammary tumorigenesis, and stem cell-like properties in breast cancer." (PMID 38380359, 2024). "In 1982, Nusse and Varmus identified the mouse Wnt1 gene, originally termed Int-1, as a favored integration locus for the mouse mammary tumor virus (MMTV) in the induction of mammary carcinomas." (PMID 37888209, 2023). "Histological analysis revealed that mammary tumors developing in mice with RSPO3/WNT1 co‐expression showed a mixed phenotype, typically exhibiting characteristics of both RSPO3‐ and WNT1‐driven tumors." (PMID 36106661, 2022). "MMTV-Wnt1 transgenic mice express Wnt1 driven by MMTV-LTR, developing breast cancer that shows luminal and basal subtype features." (PMID 35563777, 2022). "We also show that mammary tumors driven by RSPO3 are morphologically and molecularly distinct from WNT1‐driven tumors, with higher metastatic potential." (PMID 36106661, 2022).
breast cancer (continued). "Meanwhile, a study also demonstrated that HOTTIP acts as a molecular sponge for miR-148a-3p to increase WNT1 expression, thereby modulating the CSC-like properties of breast cancer, suggesting that HOTTIP is a new target for breast cancer treatment." (PMID 36338699, 2022). "In breast cancer, Six3 was transcriptionally targeted for repression by metastatic tumor antigen 1 (MTA1) which in turn upregulated Wnt1." (PMID 34490256, 2021). "Here, higher SMAD2/3 levels were detected in primary mammary tumors derived from the double transgenic mice (i.e., MMTV–Prune-1/Wnt1), compared with those from MMTV–Wnt1 models." (PMID 33426510, 2021). "For these reasons, we confirmed the activation of TGF-β in vivo in mammary tumors generated in the GEMM of metastatic Prune-1-driven TNBC (i.e., MMTV–Prune-1/Wnt1 cells)." (PMID 33426510, 2021). "In this study, we demonstrate that though FAK is dispensable for the onset of Wnt1-driven mammary tumors, disruption of FAK’s kinase activity suppressed Wnt1-driven tumor growth and progression through compromised tumor cell survival." (PMID 32493400, 2020). "Together, these results suggest that although FAK is dispensable for the onset of Wnt1-driven mammary tumors, disruption of FAK’s kinase activity suppressed Wnt1-driven tumor growth and metastasis." (PMID 32493400, 2020). "Among them is Wnt-1, which was originally named int-1 because integration of the Mouse Mammary Tumor Virus (MMTV) into its gene locus induces mammary tumors in mice." (PMID 30558303, 2018). "Consistent with this, Wnt-1 increases the CSC population and shRNA-mediated Wnt-11 silencing in a metastatic mouse breast cancer cell line reduces expression of CSC markers and tumor formation." (PMID 30558303, 2018). "Aberrant expression of Wnt-1 leads to activation of the Wnt-1/β-catenin signaling pathway, which is essential for MCF-7 breast cancer cell survival and metastasis." (PMID 27036017, 2016). "Through correlation analysis of gene expression profiles between candidate genes and miR-148a in the TCGA breast cancer patient database, we further narrowed down targets of miR-148a to four genes, INHBB, PIK3C2B, WNT1 and NRP1." (PMID 26967387, 2016). "More specifically, we over-expressed WNT1 and FGF3 in MCF7 cells, an ER(+) human breast cancer cell line." (PMID 26421711, 2015). "Interestingly, cyclin D1 expression and Akt phosphorylation were significantly lower in the Wnt1 knockdown groups, suggesting that Wnt/β-catenin signaling may positively regulate breast cancer growth through activation of the cyclin D1 and Akt signaling pathways." (PMID 26202299, 2015). "Here, we have created a humanized model of MMTV signaling, by over-expressing WNT1 and FGF3 in human breast cancer cells, namely MCF7 cells, an ER(+) cell line." (PMID 26421711, 2015). "Many members of this module, including WIF1, WNT1, SFRP1, FZD9, and FZD8 were hypermethylated and underexpressed in both luminal-A and luminal-B breast cancers but exhibiting larger deviations in DNAm and mRNA expression in the luminal-B subtype." (PMID 26664652, 2015). "Treatment of breast cancer cells with leptin exhibited striking increase in MTA1, Wnt1, β-catenin and cyclin D1 expression in comparison to untreated cells." (PMID 26036628, 2015). "WNT ligands WNT1, WNT10a and WNT4 were expressed at higher levels in normal AR cells compared to monolayer cells, however in the breast cancer cell lines, their expression was lower in the AR cells compared to monolayer cells." (PMID 23861811, 2013).
breast cancer (continued). "Our present study is an extension of our previous work, in which we proposed the co-regulated expression pattern of the WNT gene cluster (WNT-1, WNT-6, WNT-10A and WNT-10B) in human breast carcinoma." (PMID 23372744, 2013). "We previously showed that in transgenic mice bearing MMTV-Neu- and -Wnt1-driven tumors, and report here that in mice bearing MMTV-Myc-driven tumors and in human breast cancer cell lines, RARγ expression is counterproductive to the anti-cancer effects of ATRA." (PMID 22920668, 2012). "In some cases tumors induced by non-acute retroviruses have shown evidence for activation of more than one proto-oncogene in the same tumor—e.g., int-1 (Wnt-1) and int-2 in MMTV-induced mammary tumors and pim-1 and c-myc in M-MuLV-induced tumors." (PMID 21994739, 2011). "It is also possible that SDF1 directly stimulates Wnt1 tumor cells, as SDF1 has been shown to increase proliferation of human breast cancer cell lines in in vitro cultures." (PMID 20087418, 2010). "Although cyclin D1 levels were increased in Wnt1 tumors compared with normal mammary epithelium, we found an additional fourfold increase in the cyclin D1 level in Wnt/ILK double-transgenic mammary tumors." (PMID 20565980, 2010). "Together these data suggest that PEA3 factors are important contributors to Wnt1-induced breast neoplasia, and thus strengthen the rationale for PEA3 family transcription factors as anti-breast cancer targets." (PMID 20107508, 2010). "Transplantation of multiple mouse mammary tumor models into naïve recipients revealed remarkable stability of the cancer genome in MMTV-PyMT and -Wnt1 mammary models." (PMID 18394172, 2008). "Subsequent enrichment in Sca-1 positive cancer stem cells was shown for mouse mammary tumor models, such as mouse mammary tumor virus (MMTV)-Her2/neu and MMTV-Wnt1, and Thy1/CD24 expression further defined cancer stem cells in the Wnt1 model." (PMID 18241344, 2008). "We show here that, in addition to activating the canonical Wnt/β-catenin pathway, Wnt1 transactivates EGFR and stimulates ERK1/2 activity in many human breast cancer cells." (PMID 17897439, 2007). "Our approaches to prove the specificity of Wnt1 action on ERK1/2 activity relied on the use of CM in combination with the natural WNT inhibitor sFRP1 and on ectopic expression of Wnt1 in breast cancer cell lines." (PMID 17897439, 2007). "The Wnt1 transgene, driven by the mouse mammary tumor virus (MMTV) promoter, is a well-established approach for development of a mouse model to study mammary tumor development, as the Wnt1 signaling pathway is crucial for regulating cell proliferation, differentiation and development." (PMID 40740867, 2025). "The early markers Keratin 6 and Sca-1 were detected in many hyperplastic ducts and mammary tumors of Wnt-1 transgenic mice but were not increased in premalignant ducts or tumors in MMTV-Neu, MMTV-Hras, or MMTV-PyMT transgenic mice." (PMID 41303422, 2025). "KM Plot analyses revealed that Wnt1 deregulation affected overall survival in gastric and breast cancer patients and it had no impact on the survival rate of lung and ovarian cancer patients." (PMID 36056132, 2022). "The Wnt-1 signaling pathway plays a key role in the functioning of cells, but its exact role in the development of breast cancer has not yet been elucidated." (PMID 35453754, 2022). "These mice have no functional ER-α, and they have the Wnt-1 transgene, which induces mammary tumors in all female mice." (PMID 34361004, 2021). "Wnt-1 (initially named as int-1), a member of the family of Wnt ligands, was the first protooncogene identified to be activated by the nearby insertion of mouse mammary tumor virus (MMTV) proviruses in mammary tumors of infected mice." (PMID 32493400, 2020).